CDKN1A (cyclin dependent kinase inhibitor 1A)
Diseases named in the same sentence as CDKN1A in open-access papers (continued):
Sharing a sentence is not in itself a finding about the gene and the disease.
tumor (continued). "An amount of 30 chRCCs (52.6%) were CDKN1A negative, 27 tumors (47.4%) were CDKN1A positive (cut off ≥ 2% tumor cells)." (PMID 32079343, 2020). "For instance, ANRIL and P21-AS lncRNAs are located near critical tumor suppressor genes CDKN2B and CDKN1A, respectively, and knockdown of these NATs could be a potential therapy to inhibit tumor growth in multiple malignancies." (PMID 32854207, 2020). "In order to elevate the malignancy and invasion of NSCLC cells, miR-93 downregulates the expression of tumor suppressor genes including LKB1, PTEN and CDKN1A to stimulate PI3K/Akt signaling pathway and subsequently, ensure the migration and proliferation of these tumor cells." (PMID 32612456, 2020). "Analyzing in silico the MethHC database that integrates DNA methylation and mRNA expression data from the Cancer Genome Atlas (TCGA), we observed that there is no uniform pattern when comparing tumor with nontumor DNA for CDKN1A gene expression." (PMID 31514410, 2019). "For example, overexpression of miR-1207-5p reduces the expression of signal transducers and activators of transcription (STAT6), thereby activates cyclin-dependent kinase inhibitor 1A (CDKN1A) and CDKN1B to regulate the cell cycle and promote tumor cell proliferation." (PMID 31380270, 2019). "To check whether ZEB1 binds and represses CDKN1A and CDKN2A genes in human tumor cells, we conducted ChIP assays and found that ZEB1 was indeed bound to CDKN1A promoter, implying a direct regulatory role for ZEB1 to promote cell proliferation in UM cells." (PMID 28246385, 2017). "Many of these genes, including those encoding bFGF, MAPK10, MAP3K5, IL1R2, E-cadherin, Ki67, Cyclin E1, beta-catenin, 14-3-3 protein T-cell (YWHAQ), integrin alpha-V (ITGAV), integrin alpha-10 (ITGA10), CDK6, PCNA, CDKN1A, and PAK3, are related to tumor metastasis and regulation of cell migration." (PMID 28454092, 2017). "CDKN1A (p21) gene expression was significantly lower in non-functioning tumours vs controls while CDK1 expression was high in all tumour types but only reached statistical significance in GH-secreting tumours." (PMID 28649092, 2017). "In previous studies, miR-10a inhibited epithelial-to-mesenchymal transformation (EMT), apoptosis and autophagy, induced chemo-resistance, invasion, proliferation, and tumor growth thought suppressing different protein such as EphA8, BCL2L11, TFAP2C, CDKN1A, p21, and p16." (PMID 27270310, 2016). "Other known tumor suppressors such as WT1, CEBPA or CDKN1A are instead missed by our analysis." (PMID 26860319, 2016).
tumor (continued). "In our work, we tested the in vitro efficacy of GANT61 (a GLI-inhibitor) and demonstrated that this treatment could affect the viability of GIST cells and modulate the expression of key genes for tumor progression, such KIT and CDKN1A." (PMID 26544626, 2015). "Moreover, the dominant role of CDKN1A in the advanced HCC network suggests that the main function of the cell cycle signalling pathway, have evolved from cell cycle regulating to tumour suppressing." (PMID 23002138, 2012). "Tumor suppressors targeted by this cluster include PTEN, and the proapoptotic BIM and miR-106b specifically promotes cell-cycle progression by targeting cyclin-dependent kinase inhibitors p21/cdkn1a." (PMID 21461378, 2011). "However,scRNA-seq analysis showed that CDKN1A expression wasreduced in tumor hepatocytes compared with normal livercells." (PMID 41541554, 2025). "Further, by assessing changes in histone modifications in the CDKN1A promoter region, which regulates the E2F1 transcription factor, we determined that ARID1A deletion downregulates CDKN1A acetylation, diminishes P21 protein transcription, and initiates a cascade of tumor drug resistance responses." (PMID 38600891, 2024). "In our metastatic dataset along with additional primary SCLC patient tumor, circulating tumor cell‐derived xenograft, and patient‐derived xenograft (PDX) datasets, samples overexpressing MYC paralogs (MYC, MYCL, or MYCN) consistently displayed significantly lower CDKN1A expression." (PMID 37491889, 2023). "Moreover, DK1 also enhanced the expression of several other tumor suppressor genes that are related to this pathway such as FOXO, TP73, CDKN1A, Caspase, CYCS, and GADD45A while impeded the expression of other proto-oncogenes namely PIK3R3, BCL-2, IGFBP2, HGF, and FGF." (PMID 34204873, 2021). "CDKN1A expression status is a prognostic biomarker independent of tumor stage." (PMID 32079343, 2020). "Finally, analysis of polysomal RNAs from livers of CTL and TIA1 knockdown LPTENKO mice indicated that consistent with a lack of effect of TIA1 downregulation on tumor growth and progression, markers for proliferation (Mki67, Pcna, Cdkn1a, Cdkn1b, Cdc25a) and inflammation (Il1b, Tgfb) were unchanged." (PMID 35406476, 2022).
tumor (continued). "However, no report has proved that CDKN1A is a tumor suppression gene of CCA." (PMID 29970899, 2018). "Conversely, FAP displayed a weak to moderate negative correlation (−0.3 < r < 0, p < 0.05) with tumor suppressor genes, like PTEN and CDK inhibitors (e.g., CDKN1A), hinting at its potential role in driving tumor progression." (PMID 40430845, 2025). "For CDKN1A, TIGAR, and PPM1D, although some genetic alterations were observed in BC cell lines and tumor samples, no significant changes in gene expression were detected across different BC subtypes." (PMID 41345520, 2025). "To explore the role of QCCs in MEL101, we quantified tumor cells that were negative for KI67 and positive for either or both of p21 (CDKN1A) and p27 (CDKN1B)." (PMID 41473281, 2025). "Both MEF2 and p21Cip1(CDKN1A) which unlike MYOD or MYOG are poorly expressed in FN-RMS cells when activated together with MYOD and MYOG inhibit tumor growth by driving a terminal differentiation program." (PMID 33420019, 2021). "However, the long-term SAM supplementation did not affect tumor growth and hepatocyte proliferation, while it increased the total liver DNA methylation and the number of polyploid (binuclear) hepatocytes, while it decreased the level of the p21/Cdkn1a protein in the liver." (PMID 29285212, 2017). "However, the indication, obtained by target prediction, that some mRNAs highly relevant for tumor cell biology (e.g. CDKN1A and Drosha) could be differentially targeted by the non-edited, tumor enriched miR-376c isoform, is surely intriguing and deserves further investigation." (PMID 26188123, 2015). "The suppressive function of CDX2 on tumor cell proliferation observed in several studies has been explained by CDX2-mediated activation of negative cell cycle regulators, such as cyclin-dependent kinase inhibitor 1A (CDKN1A), a known inhibitor of G1 cyclin/cyclin-dependent kinase complexes." (PMID 19781065, 2009).
cancer (608 papers, 1996 to 2026). A tumor composed of atypical neoplastic, often pleomorphic cells that invade other tissues. "We also explored the expression of the underlying cancer‐promoting genes within cluster 3; these genes included Cdkn1a, Plaur, Ptgs2, Cox17, Lilrb4q, G0s2, Egr1, and Cxcl2, with previous reports suggesting their implication in increasing cancer progression." (PMID 39113226, 2024). "In terms of the mutational burden, CDKN1A mutations vary both in terms of the type of mutation and cancer." (PMID 38139316, 2023). "Our findings add CDKN1A induced by SOCS1 deficiency to this list of NRF2 activators in cancer cells." (PMID 36765862, 2023). "The cytoplasmic localisation of CDKN1A/p21 is predominantly associated with cancer, where it serves to promote tumorigenesis and inhibit apoptosis." (PMID 38139316, 2023). "Typically, these polymorphic changes lead to a reduction in the transcriptional activity of CDKN1A, consequently heightening susceptibility to cancer." (PMID 37730565, 2023). "Several studies have indicated that CDKN1A polymorphisms can impact protein expression and activity, and play a role in cancer susceptibility." (PMID 37730565, 2023). "While CDKN1A gene mutations are rare in carcinoma, a decrease in CDKN1A expression is often associated with a poor prognosis." (PMID 37730565, 2023). "This suggests that genetic polymorphisms in CDKN1A are likely to modulate its expression, thereby influencing the pathogenesis and initiation of carcinoma." (PMID 37730565, 2023). "The loss of KDM6A can reduce the expression of certain cancer suppressor genes, such as CDKN1A and PERP." (PMID 36052737, 2022). "A TSG that is commonly downregulated in cancer is cyclin-dependent kinase inhibitor 1A (CDKN1A), which encodes p21." (PMID 36700046, 2022). "The transcription of three genes associated with cancer, CDKN1A, SGK1 and CHKA, were measured using qRT-PCR." (PMID 32910239, 2021). "p21, encoded by CDKN1A gene, is a pivotal cell cycle regulator which is often deregulated in human cancer." (PMID 32562081, 2021). "Subsequent TCGA data mining and tissue microarray (TMA) analysis revealed that CDKN1A is commonly deficient in human cancers, suggesting extensive clinical application prospects for M1." (PMID 33037696, 2020). "CDKN1A is known as a critical cell-cycle checkpoint protein and is closely associated with drug resistance in cancer." (PMID 32477939, 2020). "In some cancers, the loss of CDKN1A expression upregulates genes that repress CDKN1A transcription, such as MYC." (PMID 32079343, 2020). "Several studies show an association between CDKN1A-SNPs and cancer and patient survival prognostics." (PMID 30706161, 2019). "In our study of much larger cohort of this rare cancer, univariate and multivariate logistic regression analysis shows the highly significant protective effect of CDKN1A SNP on risk of MTC development in sporadic as well as hereditary MTC." (PMID 31408923, 2019).
cancer (continued). "CDKN1A encodes p21Cip/Waf; due to its relevance to cancer, this gene was selected independently of the microarray data." (PMID 29110037, 2018). "IPA at 4 h revealed that 7 genes [Btg2, Ccng2, Cdkn1a, Gadd45b, Gadd45g, Phlda3, and Mdm2] of 18 genes, which showed statistically significant increases, were associated with cancer, cell cycle, cell death and survival, and cellular growth and proliferation." (PMID 27482301, 2016). "As a step towards this goal, we developed a computational framework capable of predicting functional connections between genes mutated in cancer, and we applied our methodology to define a network between Apc and Cdkn1a." (PMID 20824133, 2010). "Investigating the influence of MES on ferroptosis-related genes, especially ATF3, HMOX1 and CDKN1A, may provide valuable insights into the molecular mechanisms underlying its action and offer potential therapeutic strategies for cancer treatment." (PMID 39857803, 2025). "The existence of natural variants of CDKN1A has been associated with specific cancer types." (PMID 37730565, 2023). "Downregulation of cell cycle inhibitor CDKN1A is a hallmark of many cancer types." (PMID 38203204, 2023). "For instance, researchers have reported that METTL3/METTL14 catalyzes m6A modification in the 3'UTR of CDKN1A mRNA, which encodes the cyclin‐dependent kinase inhibitor p21, to promote cell cycle arrest in oxidative stress‐induced senescence of human cancer cells." (PMID 37641471, 2023). "CDKN1A is associated with cell cycle regulation and cell apoptosis in several types of cancers." (PMID 34214254, 2021). "High expression of p21 protein in head/neck, esophageal, and oral squamous cell carcinomas has been correlated with poor prognosis, indicating that loss of CDKN1A regulation could promote cancer progression in epithelial cells." (PMID 34837932, 2021). "LED (lncRNA activator of enhancer domains) and FAL1 (focally amplified lncRNA on chromosome 1) lncRNAs are able to specifically control the expression of CDKN1A gene, even though through different mechanisms, and their deregulation in cancer accounts for the loss of p21 activation." (PMID 29443889, 2018). "Indeed, some human cancers display elevated levels of cytoplasmic CDKN1A or cytoplasmic CDKN1B, which is associated with poor prognosis, and badly response to cisplatin based treatment." (PMID 28231799, 2017). "Interestingly, MBD3 protein was shown to be associated with the proximal promoter of CDKN1A and was released on treatment of cancer cells with a HDAC inhibitor." (PMID 23658227, 2013). "Furthermore, Myc (c-myc), Ccnd1 (cyclin D1), and Cdkn1a (p21/Waf1) are Notch target genes implicated in cancer." (PMID 22720165, 2012). "In human dental pulp stem cells (DPSCs), METTL3/METTL14 have been shown to catalyze m6A modification in the 3’UTR of CDKN1A mRNA, which encodes the cell cycle-dependent kinase inhibitor p21, thereby promoting cell cycle arrest in oxidative stress-induced senescence of human cancer cells." (PMID 39963130, 2025).